MEIS1 (Meis homeobox 1)
Description:
Acts as a transcriptional regulator of PAX6. Acts as a transcriptional activator of PF4 in complex with PBX1 or PBX2. Required for hematopoiesis, megakaryocyte lineage development and vascular patterning. May function as a cofactor for HOXA7 and HOXA9 in the induction of myeloid leukemias.
Tractability: Small molecule: a high-quality ligand is known. PROTAC: ubiquitination databases record sites on it.
Gene: Protein-coding gene on chromosome 2 (66,433,452 to 66,573,898, forward strand). Ensembl gene ENSG00000143995.
Subcellular location: Nucleus
Subcellular location (Human Protein Atlas): Nucleoplasm
Pathways (Reactome):
Developmental Biology: Activation of anterior HOX genes in hindbrain development during early embryogenesis
Gene Ontology:
Molecular function: DNA binding; protein binding; DNA-binding transcription activator activity, RNA polymerase II-specific; DNA-binding transcription factor activity, RNA polymerase II-specific; RNA polymerase II cis-regulatory region sequence-specific DNA binding; chromatin binding; sequence-specific DNA binding
Biological process: angiogenesis; animal organ morphogenesis; brain development; embryonic pattern specification; eye development; hemopoiesis; negative regulation of myeloid cell differentiation; positive regulation of cell population proliferation; positive regulation of transcription by RNA polymerase II; cell growth involved in cardiac muscle cell development; regulation of DNA-templated transcription
Cellular component: nucleoplasm; chromatin; nucleus; transcription regulator complex
Genetic constraint (gnomAD): Loss-of-function variants: 5 observed, 46.03 expected, observed/expected ratio (o/e) 0.11, 90% interval 0.056 to 0.23. The upper end of that interval is the gene's LOEUF score, 0.23, which puts it in group 1 of 6, group 1 being the genes least tolerant of losing a copy. Missense variants: 318 observed, 514.36 expected, observed/expected ratio (o/e) 0.62, 90% interval 0.56 to 0.68. Synonymous variants: 176 observed, 182.67 expected, observed/expected ratio (o/e) 0.96, 90% interval 0.85 to 1.09.
Homologues: Orthologues: chimpanzee MEIS1 (97% identical), dog MEIS1 (97% identical), macaque MEIS1 (97% identical), pig MEIS1 (97% identical), rabbit MEIS1 (97% identical), guinea pig MEIS1 (97% identical), mouse Meis1 (97% identical), rat Meis1 (97% identical), tropical clawed frog meis1 (96% identical), zebrafish meis1b (94% identical), Drosophila melanogaster hth (63% identical), Caenorhabditis elegans unc-62 (48% identical), and 5 more. Paralogues in human: MEIS2 (84% identical), MEIS3 (65% identical), MEIS3P2 (59% identical), PKNOX2 (40% identical), PKNOX1 (38% identical), PBX1 (25% identical), PBX3 (24% identical), PBX2 (22% identical), PBX4 (19% identical), TGIF1 (15% identical), TGIF2 (11% identical), TGIF2LX (9% identical), and 1 more.
Diseases named in the same sentence as MEIS1 in open-access papers:
MEIS1 is named in the same sentence as 147 diseases in open-access papers, as found by Europe PMC text mining. Sharing a sentence is not in itself a finding about the gene and the disease. The quoted sentences say what the papers report.
leukemia (187 papers, 2007 to 2026). A malignant (clonal) hematologic disorder, involving hematopoietic stem cells and characterized by the presence of primitive or atypical myeloid or lymphoid cells in the bone marrow and the blood. "In fact, analysis of HoxA9 and MEIS1 gene expression in children with leukemia confirmed the association of both HoxA9 and MEIS1 overexpression in different leukemia subtypes including acute myeloid leukemia (AML) and mixed lineage leukemia (MLL)." (PMID 41535654, 2026). "Together, these results show that high levels of expression of 2 key genes associated with a worse prognosis (ie, RUNX2 and MEIS1) are associated with nearby enhancer activity that is specific to an individual leukemia." (PMID 40729681, 2025). "The interaction leads to enhanced expression of leukemia-associated TFs (e.g. HoxA cluster genes, Meis1 and Mecom) and genes involved in protein translation (e.g. Myc), respectively." (PMID 35350382, 2022). "Recent studies have identified DHODH as a therapeutic target for AML, and DHODH inhibitors cause myeloid differentiation and show potent anti-leukaemia effects in several AML mouse models including the Hoxa9/Meis1 model." (PMID 36285442, 2022). "Gene expression annotation revealed distinct distributions of cells expressing leukemia-associated genes (Meis1, Hoxa9, and Myc; clustered toward the right) vs. myeloid-differentiation markers (Cd11b, Gr1, and Ltf; clustered toward the left)." (PMID 34210975, 2021). "Co-expression of HOXA9 with MEIS1 causes leukemia in mice which recapitulates MLL fusion-mediated leukemia." (PMID 34310280, 2021). "Meis1 mutations lead blood cells to develop the symptoms of leukemia, as well as gain the chemoresistance and proliferation of leukemia cells by triggering other MEIS-cofactors." (PMID 33402862, 2020). "Somewhat surprisingly, the list of target promoters failed to include most MLL-AF9 ChIP targets with the leukemia self-renewal associated Hox gene signature, namely Hoxa9, Hoxa10 and Meis1, escaping Kat2a-dependent promoter acetylation control." (PMID 31985402, 2020). "Variants in LMO1 have been associated with BMI44 and neuroblastoma and T-cell leukemia, which is of interest since the strongest genetic predictor for RLS is a variant in MEIS1 that affects cancers such as leukemia and neuroblastoma." (PMID 33239738, 2020). "Persistent expression of HOX genes along with expression of another up-regulated HOX cofactor, MEIS1, appears to be necessary and sufficient to cause and maintain leukemia." (PMID 32645016, 2020). "In cases with an inactivation mutation of Meis1 in fetal liver cells, myeloid transformation loses its capability for the differentiation and self-renewal of leukemia stem cells." (PMID 33402862, 2020). "They demonstrated that menin inhibition induced the loss of MEIS1 expression and led to the significant differentiation of Npm1c leukemic cells in vitro, with a potent anti-leukemic activity on NPM1c in pre-leukemia and in overt leukemia." (PMID 32545659, 2020). "At the level of epigenetically modified DNA, different mutations of the DNA methyl transferase protein DNMT3A are associated with modifications of the DNA methylation status, leading to a leukemia associated with HOXA9/MEIS1 expression." (PMID 31213012, 2019). "Loss of MEIS1 in high-MEIS1-expressing leukemia stem cells was associated with increased cellular ROS and heightened oxidative phosphorylation, and knockdown of MEIS1 in MLL-AF9-driven in vitro and in vivo leukemia models increased oxidative phosphorylation." (PMID 30670779, 2019). "Sustained expression of HOXA9 and MEIS1 in hematopoietic progenitors causes leukemia in mouse models, suggesting that these two genes are strong drivers of leukemogenesis." (PMID 30693017, 2018). "Meis1 is recognized as an important transcriptional regulator in hematopoietic development and is strongly implicated in the pathogenesis of leukemia, both as a Hox transcription factor co-factor and independently." (PMID 26986211, 2016).
leukemia (continued). "This aberrant histone methylation at the MLL target gene loci causes overexpression of many Hox genes (e.g., HoxA7, HoxA9, and Meis1) that eventually cause leukemia initiation." (PMID 26970896, 2016). "HLF has been previously implicated in leukemia as a fusion with E2A in B-precursor ALL as well as direct target of Meis1 in Hox-mediated transformation." (PMID 26986211, 2016). "This aberrant epigenetic event dysregulates the expression of many MLL target genes, such as HoxA9, HoxA7, and Meis1 whose overexpression can cause leukemia." (PMID 27316347, 2016). "We and others have previously shown that Hoxa9 and Meis1 act in synergy to cause leukemia in transplantation models." (PMID 27525194, 2015). "On the other hand, the Prep1i/i background appears to favor the insurgence of mutations that cause a more aggressive Meis1-HoxA9-generated leukemia." (PMID 24809472, 2014). "In bone marrow transformation assays and mouse model systems, co-expression of Meis1 and HoxA9 together cause aggressive leukemias in mice and together can replace the requirement for an active MLL-ENL fusion protein." (PMID 24213472, 2012). "In the current studies, we provide several lines of evidence demonstrating that HoxBlinc lncRNA acted as an oncogenic regulator downstream of NUP98-PHF23 to organize TAD topology and expression of HSC/leukemia-associated genes including Kit, posterior Hoxa, middle Hoxb, and Meis1." (PMID 39883527, 2025). "Overall, the expression of Meis1–3, Pbx1–3, and their associated partner, Hoxa9, were observed as upregulated in thymoma, pancreatic adenocarcinoma, glioblastoma, glioma, lymphoma, and leukemia when compared to corresponding healthy adult tissues." (PMID 33402862, 2020). "Thus, FLT3 expression was associated with HOXA5, HOXA7, HOXA9 and MEIS1 in human leukemia and this gene expression profile was confined to leukemia with either intermediate or unfavorable cytogenetics." (PMID 17712416, 2007). "Accumulating evidence further demonstrated that other drivers of leukemia also hijack WT‐Menin‐KMT2A complexes in a similar way to drive HOX/MEIS1 gene expression." (PMID 39887730, 2026). "The association of oncogenic KMT2A-fusion proteins with Menin and LEDGF is required for its chromatin binding, target gene expression such as the HOXA9 and MEIS1, and implicated the Menin-KMT2A interaction as a therapeutic opportunity in these leukemias." (PMID 40374809, 2025). "We measured MEIS1 protein levels in both LICs and the bulk of BM leukemia cells, using Western blotting, and found that the MEIS1 levels were substantially increased in Asic3-null AML cells, especially in Asic3-null LICs." (PMID 41392978, 2025). "RNA-seq analysis of A485-treated K/C-III leukemia cells further revealed significant downregulation of key hematopoietic factors, including Hoxa9, Hoxa10, Meis1, Cd34, c-Kit, and Csf1r." (PMID 40830799, 2025). "NUP98-PHF23 drives leukemogenesis by aberrantly upregulating leukemia-associated genes (e.g., HOXA cluster and MEIS1), resulting in impaired hematopoietic stem cell differentiation and leukemic transformation." (PMID 41268576, 2025). "Targeting PBX3/MEIS1 interaction is a feasible strategy for treating MLL-rearranged leukemia cells overexpressing PBX3." (PMID 38528641, 2024). "MEIS1 is related to the differentiation of leukemia stem cells and the proliferation of leukemia cells." (PMID 38167056, 2024). "Strikingly, increased H3K4 trimethylation occurred in the promoters and ORFs of several of the same genes that are frequently upregulated in MLL1F leukemias including HoxA9-13, Meis1, and ZEB1." (PMID 39342993, 2024). "In NUP98‐r, KMT2A‐r, and NPM1‐mutant leukemia, all of which induce and depend on the MEIS1/HOXA transcriptional program, small molecule inhibitors that disrupt the Menin‐KMT2A interaction have demonstrated potent antileukemic effects." (PMID 39323480, 2024).
leukemia (continued). "DOT1L, the only methyltransferase for H3K79 in mammals known to date, methylates H3K79 to activate the expression of HOXA and MEIS1 in LSCs to support the occurrence of leukaemia and to maintain the growth of MLLr leukaemia cells." (PMID 38671157, 2024). "The NPM1-mutated AML has a gene expression profile similar to KMT2Ar leukemias with the upregulation of HOX and MEIS1 genes." (PMID 38651453, 2024). "MLL1-r and NPM1c leukemias are both associated with upregulated expression of cofactors such as HOXA, MEIS1 and PBX3, which are crucial in leukemia development, cell proliferation, and self-renewal." (PMID 36841758, 2023). "Meis1 is an important transcription factor that is initially discovered in leukemic mice and its biological functions have been extensively studied in leukemia, organogenesis, embryonic development, and tumorigenesis." (PMID 36834910, 2023). "Concordant with our findings, previous studies have identified the co-upregulation of HOXA9 and MEIS1 in KMT2A-rearranged leukemias and further support that these TFs are key drivers of leukemogenesis." (PMID 38116118, 2023). "For instance, despite normal expression of HOXA and MEIS1, perturbation of the menin-KMT2A complex impairs proliferation in leukemia cell lines of mutated CEBPα AML." (PMID 38174649, 2023). "The VTP-50469 targets the expression of FLT3 by inhibiting leukemia transcription factor MEIS1 and promotes the loss of phosphorylated FLT3 mediated by FLT3 inhibitors, thus producing a synergistic antileukemia impact on NPM1mut or MLL-r leukemia." (PMID 37049787, 2023). "M-89 can also block the development of leukemia by inhibiting the expression of MEIS1 and HOX genes." (PMID 37049787, 2023). "In fact, Hoxa9/Meis1 combination is one of the most potent AML-inducing oncogenes that induce the fastest occurrence of leukaemia." (PMID 36285442, 2022). "Another menin-MLL inhibitor, MI-3454, also showed complete remission or regression of leukemia in a PDX model accompanied by downregulation of key leukemogenic genes such as MEIS1." (PMID 35216478, 2022). "Hoxa9/Meis1 combination is among the most potent AML-inducing oncogenes that induce the fastest occurrence of leukaemia in mice." (PMID 36285442, 2022). "Myeloid ecotropic virus insertion site 1 (MEIS1) is a HOX co-factor known to be necessary for normal hematopoiesis and it is implicated in a wide range of leukemias due to its deregulated overexpression." (PMID 35624144, 2022). "DSF has therefore the potential to be in interesting candidate to study in this and other leukaemias characterized by high HoxA cluster and MEIS1 expression." (PMID 35730653, 2022). "MEIS1 has been shown to act as an oncogene in leukemia but a tumor suppressor in other cancer types." (PMID 35351858, 2022). "Another study has discovered cooperation of NPM1 and IDH2 mutations for leukemia development in mice through activation of the Hoxa9/Meis1 pathway, where NPMc and IDH2/R140Q increase the expression of Hoxa9 and Meis1, respectively." (PMID 34944812, 2021). "The combinational overexpression of Hoxa9 and Meis1 leads to a massive acceleration of leukemia development." (PMID 34150668, 2021). "MLL-r leukemia has been extensively studied in the mouse by the laboratory of Michael Cleary, which has established the essential role of Meis1 in leukemia induction and maintenance." (PMID 34698191, 2021). "Another mouse study showed that wild-type CEBPA is required for KMT2A-MLLT1 driven leukemia through activation of Hoxa9/Meis1." (PMID 34944812, 2021). "Depletion of this transcriptionally activating mark by DOT1L deletion or high concentrations of the inhibitor pinometostat downregulates HOXA9 and MEIS1, and consequently reduces leukemia survival." (PMID 34263728, 2021).
leukemia (continued). "We previously found that loss of Kmt2a led to downregulation of the aberrant “MN1-driven leukemic program”, suggesting that the aberrant expression of Hoxa9 and Meis1 in MN1-driven leukemia remained under the control of its physiologic regulator, Kmt2a." (PMID 33542482, 2021). "MEIS1 plays a crucial role in normal development and it is also reported as an important gene related to leukemia." (PMID 33711952, 2021). "In agreement with the previous evidence that reduced expression of HOXA9 and MEIS1 impairs viability of leukemia cells, FGFR2 knockdown negatively affected the proliferative rate of RS4;11 leukemia cells." (PMID 33924850, 2021). "MEIS1, a critical regulator of leukemia stem cells (LSCs), is often found overexpressed in Hox-gene-driven leukemia." (PMID 34150668, 2021). "PBX3 (not PBX1 or PBX2) is apparently the most important form of PBX that interacts with MEIS1 in human MLL-r leukemias." (PMID 34698191, 2021). "Next, we assessed the effects of the combined expression of MYC, HOXA9, and MEIS1 in mouse leukemia models." (PMID 34310280, 2021). "Currently, it is well recognized that HoxA9 expression alone is only weakly oncogenic in mouse leukemia models and usually requires a second “hit”, the overexpression of Meis1." (PMID 34698191, 2021). "MLL fusion- and HOXA9/MEIS1-transduced cells, which are capable of inducing leukemia in vivo, expressed Myc 20–100% more than HOXA9-ICs." (PMID 34310280, 2021). "To dissect the underlying mechanisms of the induced anti-leukemia effect and confirm the disruption of DOT1L recruitment to MLL target gene loci Hoxa9 and Meis1, we performed a chromatin immunoprecipitation coupled with qPCR (ChIP-qPCR)." (PMID 33562706, 2021). "SEC is essential for expression of characteristic genes of MLL-r leukemia (e.g., HoxA9 and Meis1) as well as leukemia transformation." (PMID 33823889, 2021). "In human leukemia, the cooperation between MEIS1 and HOXA9 with PBX has been extensively reported; specifically, the PBX3 form appears to be the prevalent form involved." (PMID 34698191, 2021). "Formation of SEC is required for expression of characteristic genes of MLL1-r leukemia (e.g., HoxA9 and Meis1) as well as leukemia transformation." (PMID 33823889, 2021). "In PBX-MEIS1-induced human leukemia and in MEIS1-dependent mouse tumorigenesis, HOXA9 appears to have an accelerating role." (PMID 34698191, 2021). "The aberrant methylation of H3K79 by DOT1L would enhance the expression of leukemogenic genes homeobox A9 (HOXA9) and Meis Homeobox 1 (MEIS1), driving the pathogenic of mixed lineage leukemia (MLL) rearranged leukemia." (PMID 34425876, 2021). "C/EBPα−/− mice do not develop myeloid leukaemia even upon expression of Bcr-abl, and C/EBPα is required for the development of leukaemia in other models (MLL-fusion or Hoxa9/Meis1-induced leukaemia)." (PMID 34226527, 2021). "Next, compound 1 was tested for its ability to change expression of characteristic MLL-r leukemia genes HoxA9, Meis1 and Myc." (PMID 34373735, 2021). "MEIS1 overexpression has been reported in leukemia and neuroblastoma, suggesting its possible correlation with tumorigenesis." (PMID 34948208, 2021). "The combined expression of MYC/HOXA9 or MYC/MEIS1 induced leukemia in 38% and 18% of recipient mice, respectively, indicating a synergy of MYC with HOXA9 and MEIS1." (PMID 34310280, 2021). "Forced expression of HOXA9 enforces self-renewal, impairs myeloid differentiation of murine marrow progenitors, and ultimately leads to late onset of leukemia transformation, which is accelerated by co-expression with interacting partner protein MEIS1." (PMID 33001025, 2020). "In some cancers including MLL fusion leukemia, it has been reported that MEIS1 is crucial for maintenance of the stem cell molecular profile." (PMID 32819319, 2020). "Meis1–3, Pbx1–3, and Hoxa9 are upregulated in thymoma, pancreatic adenocarcinoma, glioma, glioblastoma, and leukemia/lymphoma when compared to healthy tissue." (PMID 33402862, 2020).